HLA-B (major histocompatibility complex, class I, B)
Diseases named in the same sentence as HLA-B in open-access papers (continued):
Sharing a sentence is not in itself a finding about the gene and the disease.
tumor (continued). "Staining for HLA-A, HLA-B and HLA-C was positive in on average 85% of the tumor cells (25–98%) and for the Class II antigen HLA-DR in 7% (0–58%)." (PMID 31394860, 2019). "Six of the 10 (60%) proteins examined using TMA immunohistochemistry, HLAB, protein 14-3-3β, LTBP3, ADAMTS2, JAG2 and NME2, were significantly associated with clinical parameters which have shown to relate with tumor progression, invasion and metastasis." (PMID 30679934, 2019). "We found that four out of the 21 shared ASE genes (HLA-A, HLA-B, HLA-C, and CEACAM7) and showed significant differences in the allele ratios between tumor and normal tissues (paired t-test)." (PMID 30538721, 2018). "As an example, the RBP3V282M (GESDFFFTVPMS) neopeptide that is predicted to have high affinity to HLA-B*18:01 in patient MPM.003 (TiME-I) demonstrated high abundance in this tumor." (PMID 29618661, 2018). "It has been reported that tumoral cells can upregulate HLA-A, HLA-B and HLA-C expression, decreasing the level of macrophage activation." (PMID 29228712, 2017). "This frameshift mutation was translated into a truncated protein with a 13-mer neo-peptide tail, which was predicted to be presented by the patient’s HLA-B molecule as a tumor-specific neo-antigen." (PMID 27187383, 2016). "At the metastatic LN, tumor cells also showed downregulation of HLA-A (80 %), HLA-B/C (87 %), and total classical HLA (87 %)." (PMID 27895918, 2016). "In the paired metastatic AC samples a significantly lower expression of HLA-B/C (P = 0.007, Wilcoxon Signed Rank test) and total classical HLA (P = 0.021, Wilcoxon Signed Rank test) was found compared to the primary tumor." (PMID 27895918, 2016). "Metastatic tumor cells in the LN, showed also downregulation of HLA-A (92 %), HLA-B/C (96 %), and total classical HLA (98 %)." (PMID 27895918, 2016). "We found that HLA-A, HLA-B, HLA-C genes have a similar pattern of reduction in CRPC and elevation in high risk NHT primary tumours." (PMID 27619158, 2016). "Tumors with downregulation of HLA-A (p=0.012) or HLA-B/C (p=0.018) displayed on average lower numbers of total tumor-infiltrating T cells." (PMID 26658106, 2016). "In line with the results obtained in primary tumor samples, β2-microglubulin and HLA-B were, respectively, up- and downregulated in U266 cell line when compared to RPMI-8226." (PMID 26807199, 2015). "The results showed a significant increase in the prevalence of HLA-A and HLA-B/C down-regulation in metastasised neoplastic cells as compared with the primary tumour (P = 0.01)." (PMID 8198988, 1994). "Selective losses of HLA-B antigens were also detected in 8.8, 3.4 and 5.8% of these tumours respectively." (PMID 2649129, 1989). "Based on the networks, we find several hub genes shared across spatial regions, e.g., HLA-B (weighted connectivity degrees: 0.94 for tumor; 0.23 for intermediate; 1.35 for normal), which shows negative partial correlation with GBP-1 in the normal region and positive in the tumor region." (PMID 39954675, 2025). "Additionally, genes like COL4A1, PLOD2, and PXDN, which participate in extracellular matrix remodeling, alongside immune-related genes such as CYFIP2, EMP3, and HLA-B, are instrumental in modulating the tumor microenvironment and facilitating immune evasion." (PMID 39949776, 2025). "To test this hypothesis, we first constructed ATM knockdown stable cell lines in four TNBC cell lines, MDA-MB-231, HCC1937, SUM159 and BT549, and found that the expression of MHC-I (HLA-A + HLA-B) on the surface of tumor cells was increased by flow cytometry." (PMID 40825766, 2025). "The HLA-B–HLA-E–NKG2A pathway has a role in the NK cell surveillance of tumor cells and is a target for cancer immunotherapy by inhibitory checkpoint blockade with monoclonal anti-NKG2A antibodies that enhance both NK cell and T cell activity against tumor cells." (PMID 39201555, 2024).
tumor (continued). "Expression of CCL18, IL-5RA, and HLA-B as well as macrophage tumor infiltration could identify patients who can potentially benefit from treatment with immune checkpoint inhibitors." (PMID 38790160, 2024). "Alterations in genes corresponding to major histocompatibility complex class I (eg, HLA-B or HLA-C) have been postulated to promote tumor evasion of immune surveillance (eg, by restricting neoantigen presentation), although no guideline recommendations to test HLA genes exist currently." (PMID 38508412, 2024). "Among them, HLA-B and STAT1 are well-known proteins associated with anti-tumor immunity." (PMID 37380972, 2023). "Notably, the expression of genes encoding MHC class I molecules, such as human leukocyte antigen (HLA)-A, HLA-B, HLA-C, and HLA-E, and beta-2 microglobulin, significantly decreased in After Tumor." (PMID 38136558, 2023). "Low tumor expression of HLA-A, but not HLA-B or HLA-C, was significantly associated with favorable OS prognosis in GBM patients treated with TFDC immunotherapy (p = 0.014)." (PMID 37382632, 2023). "Notably, NST ER−/HER2− cancer cells from obese patients expressed lower levels of major histocompatibility complexes class I (MHC-I) (HLA-B, HLA-C), suggesting a potential niche for evasion of anti-tumor immunity." (PMID 37479706, 2023). "Subsequently, we analyzed SQLE expression and its association with biomarkers of MHC (B2M, HLA-B, HLA-C, TAP1, and TAP2), dendritic cells (BATF3), macrophages (CD68 and IL1A), type-I anti-tumor responses (CD8A and GZMB), and cell proliferation (MKI67) in 178 PAAD tissues." (PMID 35720314, 2022). "Changes in HLA-B expression could impact the presentation and recognition of oncogenic antigens on the cell surface by cytotoxic T cells and, ultimately, limit tumor cell eradication." (PMID 36008984, 2022). "Cultures were established in a 96-well microculture format to favor stimulation of rare peptide-dependent minor histocompatibility antigens (mHAg)- or tumor antigen-specific CTLs instead of allo-HLA-B or -HLA-C mismatch reactions, which would dominate in bulk MLTC." (PMID 35681710, 2022). "Nonetheless, of the two HLA-B*07 samples (CRC1 and CRCLM1, from different patients), the liver metastasis sample presented more than twice the number of HLA-B*07 phosphopeptides, indicating that this increased presentation is actually driven by the metastatic status of the tumor." (PMID 34504498, 2021). "Here, we describe the development of a CAR targeting the tumor-specific isocitrate dehydrogenase 2 (IDH2) with R140Q mutation presented on the cell surface in complex with a common human leukocyte antigen allele, HLA-B*07:02." (PMID 34489470, 2021). "Of note, a combinatorial biomarker of HLA-B HED and tumor mutational burden (TMB) may better stratify potential responders." (PMID 34732240, 2021). "Finally, we applied a RNA IO profiling platform to assess the associations between HLA-B HED and immunophenotypic changes in the tumor microenvironment." (PMID 34732240, 2021). "The expression of T cell cytotoxicity (CD3G, CD3E, CD4, GZMA, PRF1 and TBX21), B cell MHC II and immune exhausted-related genes were abundant in metastatic sites; while MHC I inflammation related genes (HLA-B, HLA-C and IL-1A) were mostly higher in primary than recurrent tumor sites." (PMID 33476333, 2021). "Altogether, these results strongly support the hypothesis that mKRAS epitopes are processed and presented by tumor cells in the context of HLA-A*03:01, HLA-A*11:01 and HLA-B*07:02 at sufficient levels to activate recognition by mKRAS-TCR-engineered T cells." (PMID 34272369, 2021).
tumor (continued). "However, some genetic mutations, such as those in HLA-B, MEF2A, RHOA, and NAV3, were associated with a high tumor proliferation index in this study." (PMID 33747936, 2021). "Besides, the primary tumor of the right lower lobe was genotyped as HLA-A*02:03, HLA-A*11:01, HLA-B*55:02, HLA-B* 40:01, HLA-C*12:03, and HLA-C* 07:02 using a modified computing method." (PMID 34094914, 2021). "In addition, patients with loss of human leukocyte antigen A (HLA-A) and/or HLA-B expression showed statistical significance in one-year PFS (30.9%) compared to patients with HLA-A/HLA-B tumor expression (5.6%)." (PMID 34066342, 2021). "Moreover, the top three downregulated pairs in LUAD tumor cells were HLA-B and its ligand LILRB2, GAS6-AXL, and VIM-CD44." (PMID 32549766, 2020). "CD8+ T cells recognize tumor peptides presented by major HLA-I genes (HLA-A, HLA-B, and HLA-C)." (PMID 33575208, 2020). "To test whether the expression level of HLA-B is correlated with the inflammatory state of a tumor in clinical samples, we examined the cancer genome atlas (TCGA) lung cohort (n = 1,128)." (PMID 30833945, 2019). "Expression of HLAB, ADAMTS2, LTBP3, JAG2 and NME2 on tumour cells, was associated with tumour progression and invasion, metastasis and CRC specific survival may serve as potential biomarkers to stratify CRC patients into low and high risk of tumour metastasis." (PMID 30679934, 2019). "The assumption arose that a decreased expression of HLA-A and HLA-B could prevent the development of metastasis because of NK cell-mediated lysis of migrating tumor cells in the blood, preventing the tumor cells from reaching the liver." (PMID 31394860, 2019). "Thus, we confirm binding of the two tumor neoepitopes to recombinant HLA-B*15:01 prepared through in vitro refolding." (PMID 29441070, 2018). "These protective or high risk alleles even though were frequent in our population (HLA-B*40 g.f.= 0.080 and -B*08 g.f. = 0.046) associations were not statistically significant neither for risk not for protection to the development of the neoplasm." (PMID 19196481, 2009). "Furthermore, analysis of tumor cells in the GSE149614 dataset revealed that “don't eat me” ligands CD47, CD24, human leukocyte antigen A (HLA‐A), and HLA‐B were significantly upregulated in tumor cells from NUPR1‐high samples, indicating a potential effect of NUPR1+ macrophages on tumor cells." (PMID 40305758, 2025). "The results confirmed this hypothesis: 10%, 50%, 25%, and 100% of the tumor-infiltrating groups annotated with HLA-A*02, HLA-A*11, HLA-B*08, and HLA-B*35 tetramers, respectively, were enriched in their respective HLA contexts, which were higher than the percentage of any other tetramers." (PMID 38488909, 2024). "Angiogenesis-related genes (FLT1, KDR, SPARC, INSR, ANGPT2, and FLT4) and MHC-I molecules (HLA-A, HLA-B, HLA-C, HLA-E, and HLA-F) were highly expressed in cluster 3 ECs, indicating that the cells may function as antigen-presenting cells and promote tumor parenchymal angiogenesis." (PMID 37533434, 2023). "For the other HLA alleles, especially of the HLA-B type, a quite heterogeneous presence was observed but could not be attributed to a certain tumor localization." (PMID 35954492, 2022). "Interestingly, many pathogen evasion or tumor progression strategies involve the targeting of the TAP transporter, inducing the cell surface expression of partially peptide-deficient HLA-I, as illustrated for HLA-B*35:01." (PMID 29741477, 2018). "However, more importantly, we found a significantly lower expression of classical HLA class I in SCC paired metastatic tumor cells for HLA-A (P < 0.001, Wilcoxon Signed Rank test), HLA-B/C (P = 0.005, Wilcoxon Signed Rank test), and total classical HLA (P < 0.001, Wilcoxon Signed Rank test)." (PMID 27895918, 2016).
tumor (continued). "In addition, interaction analyses of HLA expression and CD8+ T-cell infiltration led to the novel observation that the prognostic effect of a dense CD8+ T-cell tumor infiltration is only retained when tumors display a high expression of classical HLA class I, in particular HLA-B/C." (PMID 26658106, 2016). "We further sorted MARCO+ and MARCO‐ TAMs from RCC tumor tissues and performed transcriptome analyses, which confirmed the downregulation of antigen‐presentation pathway and MHC‐I genes (HLA‐A and HLA‐B) in MARCO+ TAMs." (PMID 41117057, 2025). "Genes such as HLA-B, TGM2 and GBP1 tend to exhibit high connectivity degrees across most tumor and normal regions." (PMID 39954675, 2025). "We validated the presence of WIDs in two independent genes (HLA-B and GNAS) in patient-derived tumor samples through PCR amplification of a region spanning the deleted introns, followed by Sanger sequencing." (PMID 40348775, 2025). "Specifically, the involvement of human leukocyte antigen (HLA) class I molecules (such as HLA‐A, HLA‐B, HLA‐C, HLA‐E and HLA‐F) and CD8A/B was consistently observed in the interactions between malignant cells and CD8 T cells in both tumour types." (PMID 39601163, 2024). "Immune-related proteins were first analysed, and we revealed that IFN-γ increased not only tumour cell PD-L1 but also antigen peptide transporter 1 (TAP1), HLA-A, HLA-B, HLA-C and ICAM-1, indicating strong adhesion and enhanced immunogenicity." (PMID 38719909, 2024). "We observed a significant negative correlation (Pearson’s r ≤ −0.3 and P ≤ 0.01) between HLA-B gene expression and the degree of methylation in both the TSS1500 and the gene body region in the TCGA LUAD, LUSC and ER+ tumor samples." (PMID 39358601, 2024). "It specifically highlights genes associated with antigen processing and presentation, such as HLA-B, HLA-A and HLA-DRB1 and their possible effects on tumour progression and immune evasion." (PMID 38660159, 2024). "Tumor cells can express various MHC class I molecules (e.g., HLA-A, HLA-B, and HLA-C) on their surface, which present tumor-specific antigens to CD8+ T cells." (PMID 39014148, 2024). "In contrast, aT-sEVs downregulated the expression of PD-L1, TAP1, HLA-A, HLA-B, HLA-C and ICAM-1 in tumour cells." (PMID 38719909, 2024). "Conversely, DCs in solitary primary tumours showed high expression of MHC class I molecules (HLA‐F, HLA‐E, HLA‐C, HLA‐B, HLA‐A)." (PMID 39601163, 2024). "Because of the frequent HLA-B and TAP transcriptional silencing in pediatric tumors, the identification of TAP-independent epitopes could also provide relevant T cell targets, particularly in HLA-A2-positive patients, as reported for TAP-deficient adult tumor cell lines and in preclinical studies." (PMID 38318504, 2023). "Malignant cell clusters shared cancer characteristics and widely significantly overexpressed HLA-A, HLA-B, MCL1, HDAC1, LCK, HSPB1, and IL6R, indicating a common tumor origin." (PMID 36131282, 2022). "Post hoc analyses of pretreatment tumor specimens via targeted sequencing indicated that ERBB2 amplification, RTK/RAS pathway alterations, and high neoantigen load corrected by HLA-B were positively related to survival." (PMID 36224176, 2022). "Similar results were obtained for the other MHC class I genes HLA-B and HLA-C, suggesting that the immune system plays a role in controlling hypermutated MSI/CMS1 tumours in the early stages of the disease." (PMID 35747143, 2022). "To assess the roles of PYGL and HLA-B in CRC, we further examined the expression of these two genes sequenced from normal and tumor samples." (PMID 35204406, 2022). "Considering the immune activation in FAC2 bulk samples, we checked the expression of MHC-I (HLA-A and HLA-B) and MHC-II (HLA-DRA) molecules, and found their upregulation in FAC2-like tumor cells." (PMID 35342352, 2022).
tumor (continued). "This was further supported by the high levels of MHC I/II molecules (HLA–B, HLA-C, HLA-DRB1 and HLA-DQA1) expressed in cDC-CD1C-AREG from low tumor infiltration group as well as inflammatory cytokines and chemokines (IL1B, VEGF and CCL4, etc.)." (PMID 36532059, 2022). "Several genes of antiviral immune response pathways such as HLA-B, HLA-C, HLA-DQB1 IFI6, IFITM3, CD74, and tumor suppressor genes EFEMP1 and EGR1, are upregulated in tumor and downregulated in TAS." (PMID 34316327, 2021). "Strikingly, a large proportion of the IFNγ signature genes were upregulated by SHP2 inhibition specifically in tumor cells in co-culture, including cytokines (CXCL9, CXCL10, CXCL11 and CCL5) and antigen presenting machinery (HLA-A, HLA-B and B2M)." (PMID 33446805, 2021). "In parallel, tumor cells isolated from MCS–monocytes coculture expressed the “do not eat me” signal CD47 as well as PD-L1 and HLA molecules (HLA-A and HLA-B), which are recognized ligands for PD-1 and LILRB1, respectively." (PMID 33922336, 2021). "In stimulating the process of tumor cell apoptosis, XQD plays a role in HLA-B on dendritic cells (MHC I) of mature DC and CD8+T cells at the same time, to activate CD8+T cells in the immune response, to identify tumor antigen and kill tumor cells." (PMID 31905767, 2019). "HLA class I expression was determined on whole tumour sections by immunohistochemistry using the antibodies HCA2 (HLA-A), HC10 (HLA-B/C) and β2-microglobulin." (PMID 27853827, 2017). "Conversely, tumor cells in regions with low or no CD8 + T cell infiltration exhibited reduced HLA-B levels and lacked enrichment at the cell surface in most cells." (PMID 40894019, 2025). "We observed consistently higher expression levels of MHC class I genes (HLA-A, HLA-B, HLA-F, HLA-E, B2M) in tumor cells from non-progressors to progressors." (PMID 39753553, 2025). "Importantly, we found HLA-B, HLA-E, and PSMB10 all related to antigen presentation to be enriched among down-regulated genes in tumours with high LEF-1 expression suggesting an adverse impact of Wnt/β-catenin pathway on tumour recognition by immune cells." (PMID 40130164, 2025). "The team led by Weijian Liu in China utilized scRNA-seq technology to characterize the immunosuppressive tumor microenvironment profile of osteosarcoma (OS) and discovered that MHC-I (HLA-A, HLA-B, and HLA-E)/B2M genes were downregulated, indicating diminished tumor immunogenicity in OS." (PMID 40191187, 2025). "Additionally, we have found HLA-B as a hub gene across all regions and is negatively correlated with GBP1 in the normal region and positive partial correlation in the tumor region." (PMID 39954675, 2025). "The HLA-B −21M/T genotype was an independent predictive parameter of the progression-free survival (HR = 2.08, p = 0.01) and the OS (HR = 2.059, p = 0.039) of BC patients treated with BCG, together with age and tumor histopathologic characteristics." (PMID 39857739, 2025). "Utilizing CellChat, we uncovered a nuanced interaction between macrophage-expressed HLA-B and T-cell-harbored CD8A within the tumor microenvironment, which may be crucial for shaping immunotherapeutic strategies and enhancing immunosurveillance mechanisms." (PMID 39081317, 2024). "Elevated expression of HLA-B may contribute to enhancing the immune system’s recognition and attack against GBM cells, potentially exerting a positive effect on inhibiting tumor growth." (PMID 38627939, 2024). "We next tested the association of primary/metastasis-specific downregulation of an MHC class I metagene signature composed of a composite expression of HLA-A, HLA-B, HLA-C, B2M, TAP1, TAP2 and NLRC5 between metastasis and matched primary tumor according to intrinsic subtype." (PMID 36585450, 2023). "Besides, the highest HLA-I score and HLA-II score were detected in the Hot tumor cluster, evidenced by the expressions of the corresponding MHC molecules (e.g., HLA-B/C/E)." (PMID 36991000, 2023).